RAD23B (RAD23 nucleotide excision repair protein B)
Diseases named in the same sentence as RAD23B in open-access papers:
RAD23B is named in the same sentence as 52 diseases in open-access papers, as found by Europe PMC text mining. Sharing a sentence is not in itself a finding about the gene and the disease. The quoted sentences say what the papers report.
breast carcinoma (9 papers, 2013 to 2024). "In relation to DNA single-strand break repair genes, a case–control study in Puerto Rico tested associations between SNPs in the xeroderma pigmentosum (XPC and XPD) and ultraviolet (UV) excision repair protein (RAD23B) genes and breast cancer risk." (PMID 30781715, 2019). "For example, SNPs in RAD23B have been linked to esophageal and bladder cancers and one SNP near RAD23B was strongly associated with breast cancer in a genome-wide association study." (PMID 23637977, 2013). "Finally, we screened out RAD23B as a favorable target and indicated its expression was associated with breast cancer progression, drug resistance, and poor prognosis in BRCA patients by performing real-time RT-PCR, cell viability, and IC50 assay." (PMID 36341328, 2022). "Gene RAD23B is involved in global genome nucleotide excision repair and in humans it has been associated with breast cancer but significant associations in cattle are unknown until now." (PMID 32599723, 2020). "They hypothesized that genetic variation in the nucleotide excision repair pathway genes could modulate DNA repair capacity and contribute to breast cancer risk and found an association between RAD23B and breast cancer risk, and between XPC and RAD23B and DNA repair capacity in the cases." (PMID 30781715, 2019). "In line with this, a novel breast cancer signature consisting of CRGs such as PGK1, SLC52A2, and RAD23B has shown potential for prognosis prediction, with RAD23B emerging as a promising target linked to disease progression and drug resistance." (PMID 39867656, 2024). "To further explore the expression pattern of RAD23B in breast cancer, we examined the mRNA expression level of RAD23B in 34 pairs of breast cancer tissues and adjacent normal breast tissues." (PMID 36341328, 2022). "The results of RT-PCR, cell viability, and the IC50 assay illustrated that RAD23B expression was positively correlated with breast cancer progression, drug resistance, and poor prognosis in BRCA patients." (PMID 36341328, 2022). "The protein and mRNA expression levels of RAD23B were significantly higher in breast cancer tissues than in paraneoplastic tissues, and its expression was positively correlated with poor prognosis in BRCA patients." (PMID 36341328, 2022). "It suggested that RAD23B was significantly overexpressed in breast cancer tissues than in adjacent normal breast tissues, and its expression was positively correlated with pathological grade." (PMID 36341328, 2022). "In breast cancer, RAD23B knockdown increases cell invasion and adhesion." (PMID 34512150, 2021). "The transcriptional expression of RAD23B was examined in breast epithelial cell lines (MCF10A), luminal breast cancer cells (MCF7), and triple-negative breast cancer cells (MDA-MB-231, SUM-159, and BT549)." (PMID 36341328, 2022). "A mechanistic study by Crosby and coworkers found that the forced expression of miR-373 induces a reduction in NER proteins, RAD23B and RAD52, in the breast cancer cell line MCF-7." (PMID 31191653, 2019).
prostate carcinoma (5 papers, 2015 to 2025). A carcinoma that arises from epithelial cells of the prostate gland. "Polymorphism rs817826, located between the RAD23B and KLF4 genes, has been identified as being associated with prostate cancer susceptibility though a mechanism is yet to be realized." (PMID 41413636, 2025). "For prostate cancer (PrCa), rare mutations inBRCA2 and BRCA1 give rise to moderately elevated risk,whereas two of ∼100 common, low-penetrance PrCa susceptibilityvariants identified so far by genome-wide association studies implicateRAD51B and RAD23B." (PMID 26964030, 2016).
cutaneous T-cell lymphoma (4 papers, 2014 to 2021). "A genome-wide screen revealed RAD23B, a protein that shuttles ubiquitinated proteins to the proteasome, is a biomarker for sensitivity to HDAC inhibition in cutaneous T-cell lymphoma, and this relationship has been further demonstrated to also apply in sarcomas." (PMID 28056055, 2017).
gastric cancer (4 papers, 2021 to 2024). A primary or metastatic malignant neoplasm involving the stomach. "Previous research has reported that the overexpression of the deubiquitinase PSMD7 promotes gastric cancer cell proliferation, invasion, and cisplatin resistance by stabilizing RAD23B." (PMID 39469643, 2024). "Stabilizes RAD23B by deubiquitination, which in turn promotes proliferation, invasion and cisplatin resistance in gastric cancer." (PMID 39115875, 2024). "PSMD7 is particularly important in maintaining chemoresistance, as seen in its role in stabilizing RAD23B in gastric cancer, contributing to resistance against cisplatin treatment." (PMID 39469643, 2024). "Moreover, PSMD7 can enhance the deubitization of RAD23 homolog B (RAD23B) protein, reduce the degradation of RAD23B, and promote the proliferation, invasion and cisplatin resistance of gastric cancer cells." (PMID 38494478, 2024).
amyotrophic lateral sclerosis (3 papers, 2019 to 2025). Amyotrophic lateral sclerosis (ALS) is a neurodegenerative disease characterized by progressive muscular paralysis reflecting degeneration of motor neurons in the primary motor cortex, corticospinal tracts, brainstem and spinal cord. "Deficiency of RAD23B may affect the normal functioning of motoneurons, which has further implications in the context of Amyotrophic Lateral Sclerosis." (PMID 39727940, 2024). "RAD23B is involved in DNA repair and neurodegeneration in neurodegenerative diseases such as amyotrophic lateral sclerosis, while MAP2K1 plays a critical role in synaptic plasticity and neurotransmission in addiction and psychiatric disorders." (PMID 40438583, 2025).
colorectal cancer (3 papers, 2023 to 2025). A primary or metastatic malignant neoplasm that affects the colon or rectum. "This study aimed to explore the role of RAD23B in promoting colorectal cancer (CRC) metastasis and to elucidate the underlying molecular mechanisms." (PMID 41179295, 2025).
non-small cell lung carcinoma (3 papers, 2020 to 2024). A group of at least three distinct histological types of lung cancer, including non-small cell squamous cell carcinoma, adenocarcinoma, and large cell carcinoma. "Additionally, circ-RAD23B has been found to impede the progression of non-small cell lung cancer by modulating the miR-142-3p/MAP4K3 axis." (PMID 38289973, 2024). "Circular RNA circ-RAD23B promotes cell growth and invasion by targeting miR-593-3p/CCND2 and miR-653-5p/TIAM1 pathways in non-small cell lung cancer." (PMID 32228518, 2020).
Alzheimer disease (2 papers, 2019). A progressive, neurodegenerative disease characterized by loss of function and death of nerve cells in several areas of the brain leading to loss of cognitive function such as memory and language. "The mRNA levels of RAD23B were significantly higher in the brain tissue than in blood samples in neurodegenerative diseases, such as Alzheimer’s disease patients." (PMID 31611906, 2019).
hepatocellular carcinoma (2 papers, 2015 to 2024). A malignant tumor that arises from hepatocytes. "In a case-control study, it could be indicated that a single nucleotide polymorphism (SNP) rs1805329 (Ala249Val) in Rad23B was significantly associated with the development of hepatocellular carcinoma in HCV-infected patients." (PMID 38230952, 2024).
lung carcinoma (2 papers, 2024 to 2025). "Their study detected 15 Chr9 proteins highly selective for lung cancer in comparison to healthy lung tissue (i.e., RAD23B, RPS6, ARPC5)." (PMID 38539567, 2024). "RAD23B, a critical gene involved in DNA damage repair, has emerged as a key player in driving tumor progression across several cancers, including breast and lung cancers." (PMID 41179295, 2025).
rectal cancer (2 papers, 2021). A primary or metastatic malignant neoplasm that affects the rectum. "RAD23B expression is elevated in tumors specimens, but in rectal cancer, so far, there are no studies that evaluate this possible marker for prediction of response." (PMID 34207124, 2021). "RAD23B is expressed in circulating tumor cells (CTCs) from locally advanced rectal cancer patients who do not respond to neoadjuvant chemoradiation." (PMID 34512150, 2021).
sarcoma (2 papers, 2013 to 2017). A usually aggressive malignant neoplasm of the soft tissue or bone. "Neither RAD23B nor ERCC2 have been linked to any type of sarcoma." (PMID 23637977, 2013).
bipolar disorder (1 paper, 2024). A disorder of the brain that causes unusual shifts in mood, energy, activity levels and the ability to carry out day-to-day tasks. "Finally, a differential expression of RAD23B and PIAS1 was detected in the ASD, schizophrenia and bipolar disorder datasets." (PMID 39727940, 2024).
bladder cancer (1 paper, 2008). "Garcia-Closas evaluated the influence of common genetic variation in the NER pathway on bladder cancer risk by analyzing 22 single nucleotide polymorphisms (SNP) in seven NER genes (XPC, RAD23B, ERCC1, ERCC2, ERCC4, ERCC5, and ERCC6)." (PMID 19055767, 2008).
colon cancer (1 paper, 2022). "More specifically, the APEX1 signaling pathway plays a crucial role in regulating colon CSC growth, whereas FEN1, FANCG and RAD23B were up-regulated in chemo-resistant human colon cancer cell lines." (PMID 35805102, 2022).
colorectal adenocarcinoma (1 paper, 2022). The most common type of colorectal carcinoma. "A total of 961, 500, and 500 tumors as well as 836, 413, and 434 paracarcinoma normal tissues from 993, 509, and 509 subjects with colorectal adenocarcinoma were informative for CORO1C, RAD23B, and ARPC5, respectively." (PMID 35589723, 2022).
demyelinating disease (1 paper, 2019). A broad group of disorders that affect the myelin sheaths that cover the neurons. "However, the specific mechanism of PTPRF and RAD23B in immune-mediated demyelinating diseases remains to be confirmed." (PMID 31611906, 2019).
esophageal cancer (1 paper, 2024). A primary or metastatic malignant neoplasm involving the esophagus. "In specifically, circ-RAD23B regulates PARP2 and AKT2 by sponging miR-5095 in esophageal cancer." (PMID 38289973, 2024).
laryngeal carcinoma (1 paper, 2019). Carcinoma that arises from the laryngeal epithelium. "HR23B is well known for its role in global genome nucleotide excision repair (GG-NER) and genetic polymorphisms in RAD23B are modifiers of laryngeal cancer risk in human." (PMID 30867060, 2019).
neuropathic pain (1 paper, 2022). Chronic pain caused by damage to nerve fibers. "A novel KLF2/lncRNA SNHG12/miR-494-3p/RAD23B axis might provide new insight for developing novel diagnosis or therapeutic targets for neuropathic pain." (PMID 35624111, 2022). "We elucidated the functional role of miR-494-3p in SNI-induced neuropathic pain, and we found that lncRNA SNHG12 played its role in SNI-induced neuropathic pain through regulating RAD23B protein expression in the DRGs of SNI rat models." (PMID 35624111, 2022).
ovarian carcinoma (1 paper, 2022). A malignant neoplasm originating from the surface ovarian epithelium. "Expression of circular RNA Rad23b was high in ovarian cancer tissues." (PMID 36214631, 2022). "In the obese mice, ovarian protein abundance of RAD23B was increased by PFOA exposure, which might indicate that there is an increase in DNA damage that might lead to ovarian cancer or other reproductive effects." (PMID 36214631, 2022).
prostate tumor (1 paper, 2015). "We have also detected eQTLs for RAD51B within the EuroBATS data only and for RAD23B in normal prostate TCGA data, but not in prostate tumor." (PMID 26025378, 2015).
tumor (17 papers, 2013 to 2025). "Like the seed microRNA and missense mutation SNPs in CYP1B1 that were strongly associated with tumor mutations in the present study, some of the identified RAD23B and ERCC2 SNPs also have potentially functional roles." (PMID 23637977, 2013). "Immunohistochemical analysis revealed that both RAD23B and Integrin β1 proteins exhibited higher expression levels in tumor tissues than in surrounding healthy tissue." (PMID 41179295, 2025). "IHC analysis of CRC and adjacent normal tissues revealed significantly higher expression levels of both RAD23B and Integrin β1 in tumor tissues relative to the normal tissues." (PMID 41179295, 2025). "Other studies reported that nuclear RAD23B was a potential tumor suppressor and was decreased in the tumor tissue in women with BC." (PMID 36835443, 2023). "First, higher levels of CORO1C and RAD23B expression were positively correlated with tumor invasive depth, distant metastasis (M staging), and/or LNM (N staging)." (PMID 35589723, 2022). "The evaluation of thymidylate synthase (TYMS) and RAD23 homolog B (RAD23B) expression in circulating tumor cells (CTCs) provides complementary clinical information." (PMID 34207124, 2021). "In summary, PSMD7 was highly expressed in GC and contributed to the malignant behavior and DDP resistance of tumor cells by stabilizing RAD23B." (PMID 34512150, 2021). "In this small, yet novel, case-only study of genetic risk factors for GIST tumor subtypes we identified several variants in CYP1B1, RAD23B, GSTM1, and ERCC2 that we believe are worthy of further investigation." (PMID 23637977, 2013). "Their expression levels were positively correlated, and high Integrin β1 expression was notably related with lymph node metastasis, suggesting that RAD23B may enhance tumor metastatic potential by regulating Integrin β1." (PMID 41179295, 2025). "In contrast, positive immunostaining for CORO1C, RAD23B, and ARPC5 was observed in 55.7% (535/961), 84.0% (420/500), and 85.8% (429/500) of the CRC tumor tissues, respectively, showing significant upregulation compared with the adjacent noncancerous tissues (all P < 0.0001)." (PMID 35589723, 2022). "In a preliminary study with 30 patients, we showed that thymidylate synthase (TYMS) and RAD23 homolog B (RAD-23B) expression in CTCs before and after NCRT could predict tumor response in LARC patients." (PMID 34207124, 2021). "Thus, this study aimed to clarify the role of RAD23B in CRC metastasis and to explore the molecular mechanisms by which it regulates tumor cell migration, invasion, and metastasis through the Talin1/Integrin β1/PI3K/AKT/matrix metalloproteinase 9 (MMP9) signaling axis." (PMID 41179295, 2025). "Currently, there are no relevant studies on the CORO1C, RAD23B, and ARPC5 proteins in CRC, except for our very recent work, which showed that RAD23B was overexpressed in CRC tumor tissues and associated with pathological grade, TNM staging, liver metastasis, and poor overall survival." (PMID 35589723, 2022). "Based on TCGA data, this signal is also an eQTL for RAD23B in normal prostate tissue but not tumor." (PMID 26025378, 2015). "Combined with the findings that the CORO1C, RAD23B, and ARPC5 concentrations in urine show good performance in distinguishing early-stage CRC (stage 0 and stage I) from HCs, these findings strongly suggest alterations in urinary proteins may occur at the tumor initiation stage." (PMID 35589723, 2022).
cancer (12 papers, 2010 to 2025). A tumor composed of atypical neoplastic, often pleomorphic cells that invade other tissues. "We performed this meta-analysis including 10837 cases and 13971 controls to estimate the association between RAD23B Ala249Val polymorphism and cancer risk." (PMID 24643114, 2014). "RAD23B Ala249Val (rs1805329 C>T) is one of the important polymorphisms and it encoding protein involved in DNA damage recognition, which influence cancer susceptibility in individuals." (PMID 24643114, 2014). "A number of studies have investigated associations of genetic variation in RAD23B Ala249Val (rs1805329 C>T) with cancer susceptibility; however, the findings are inconsistent." (PMID 24643114, 2014). "Despite some limitations, this meta-analysis indicates that it is unlikely that the RAD23B 249Val/Val polymorphism may contribute to the individual susceptibility to cancer risk." (PMID 24643114, 2014). "Meta-analysis of the association between RAD23B Ala249Val polymorphism and cancer risk." (PMID 24643114, 2014). "Although the exact mechanisms of how RAD23B Ala249Val polymorphism affects cancer risk at the molecular level remain unknown, the established knowledge on the structural and biological functions of the RAD23B gene may imply the potential effect of this polymorphism." (PMID 24643114, 2014). "Radiation sensitive 23 homolog B (RAD23B), a gene involved in DNA repair, cell cycle control, and tumorigenesis, has recently gained attention for its role in cancer metastasis." (PMID 41179295, 2025). "Our data suggest that PSMD7 is a novel oncogene in GC, and it contributes to the malignant behavior and DDP resistance of cancer cells by deubiquitinating and stabilizing RAD23B." (PMID 34512150, 2021). "Marked induction of RAD23B during serum deprivation of synovial fibroblast is a phenomena that will be further studied in another cell types including cancer cells, in which an decrease of RAD23B expression has been documented." (PMID 30533198, 2018). "The nucleotide excision repair (NER) protein, Rad23b, was found to be downregulated in hypoxic cancer cells." (PMID 20553627, 2010). "Top-ranked candidate cancers related to circ-RAD23B predicted by AutoEdge-CCP." (PMID 38289973, 2024). "The role of RAD23B in different types of cancers is inconsistent." (PMID 34512150, 2021). "The downregulation of Rad23b in hypoxic cancer cells could be partially reversed by antisense inhibition of miR-373, indicating a key role of miR-373 in modulating the basal expression of Rad23b." (PMID 20553627, 2010). "Although there is little evidence of a link between cancer and the specific RAD23B, ERCC2, and GSTM1 variants identified here, previous studies have observed associations between one or more types of cancer and other variants on these three genes." (PMID 23637977, 2013).
infection (1 paper, 2024). The state of being infected such as from the introduction of a foreign agent such as serum, vaccine, antigenic substance or organism. "To ensure that we can replicate the effects of Rad23A and Rad23B knock-down on HCV JcR2a infection with an untagged virus, we performed focus-forming unit (FFU) assays using the parental virus of JcR2a, Jc1, in Huh-7.5 cells." (PMID 38230952, 2024).
neurological disorders (1 paper, 2024). "However, as far as our knowledge is concerned, the impact of the dysregulation of RAD23B and PIAS1 in the neurological disorders analyzed in our work is still to be determined." (PMID 39727940, 2024).
RAD23B also shares sentences with these, for which no sentence is quoted: neurodegenerative disease (3 papers); xeroderma pigmentosum (3); melanoma (2); multiple myeloma (2); Xeroderma pigmentosum complementation group C (2); autism spectrum disorder (1); frontotemporal dementia (1); glaucoma (1); Huntington disease (1); liver cancer (1); lung squamous cell carcinoma (1); lymphoma (1); mesenchymal tumors (1); mesothelioma (1); motor neuron disease (1); myeloid malignancies (1); Parkinson disease (1); Parkinsonism (1); psychiatric disorder (1); renal cell carcinoma (1); schistosomiasis (1); schizophrenia (1); skin cancer (1); spinocerebellar ataxia type 3 and 7 (1); triple-negative breast carcinoma (1); xeroderma pigmentosum group C (1).